PIK3CA (phosphatidylinositol-4,5-bisphosphate 3-kinase catalytic subunit alpha)
Diseases named in the same sentence as PIK3CA in open-access papers (continued):
Sharing a sentence is not in itself a finding about the gene and the disease.
tumor (continued). "Interestingly, TTN, PIK3CA, MUC4, KMT2C, and MUC16 were the top mutations in both cohorts, which were reported to regulate various tumor biological processes in CC, indicating that they are less participated in the process of immune infiltration but mainly involved in tumorigenesis and progression." (PMID 33553190, 2021). "If tumor tissue is not available, plasma specimens and liquid biopsy may also assess PIK3CA mutations." (PMID 34609096, 2021). "Therefore, PIK3CA may regulate tumor cellular progression and immune infiltration by uniting CD8+ T cells and macrophages, thus affecting KIRC patients' survival." (PMID 34367282, 2021). "In addition, ARID1A and PIK3CA mutations were found to cooperate to promote tumor growth through sustained IL-6 overproduction, and IL-6 was identified as a physiological target of ARID1A tumor suppressor activity." (PMID 33758607, 2021). "No PIK3CA mutations were identified in HER2-positive tumours." (PMID 33933113, 2021). "There were no cases of HGSOC with PIK3CA mutation with MAF ≥ 1% in the tumor." (PMID 34172890, 2021). "Clinically actionable PIK3CA mutations in exons 9 and 20 have been previously found in the EGFR-mutant tumours of patients with acquired resistance to first- and second-generation EGFR-TKIs5,28–30 and could have been selected as a result of TKI selective pressure." (PMID 33741979, 2021). "In conclusion, this study showed that a corresponding circulating PIK3CA mutation was identified in 55% of non-metastatic IBC patients with baseline somatic PIK3CA mutations in tumour tissue and with detectable cfDNA, while no circulating mutation was found among patients with no PIK3CA mutations." (PMID 34911971, 2021). "Our results highlight that a corresponding circulating PIK3CA mutation was identified in 55% of non-metastatic IBC patients with a baseline somatic PIK3CA mutation in tumour tissue and with detectable cfDNA, while no circulating mutation was found among patients with no PIK3CA mutations." (PMID 34911971, 2021). "Interestingly, use of PI3K inhibitor, BYL719, in treatment of xenografts, with targeted sequencing confirming a PIK3CA E545K mutation, failed to decrease tumor growth." (PMID 34062753, 2021). "No tumour samples had co-occurring PIK3CA and ERBB-family mutations." (PMID 33933113, 2021). "Furthermore, PIK3CA mutations in nontumor cells, if any, were considered to be sporadic mutations without clonal expansion, unrelated to mutations in the tumor epithelium, and associated with low MAF." (PMID 34172890, 2021). "An unmet need therefore remains for patients whose tumours do not carry PIK3CA hotspot mutations." (PMID 32035020, 2020). "Therefore, ICI treatment may change the metabolism of tumor cells and T cells and relieve the inhibition of the antitumor effect of T cells, which allows patients with ARID1A and PIK3CA mutations to gain clinical benefits." (PMID 33363171, 2020). "PIK3CA (Phosphatidylinositol-4,5-bisphosphate 3-kinase catalytic subunit alpha) is the most frequently mutated oncogene for HNSCC (approximately 20%) and may play a role in both HPV-negative and HPV-positive tumours." (PMID 32731484, 2020).
tumor (continued). "The central role of PI3K activation in tumor cell biology has prompted an effort to target PI3K and/or downstream kinases such as AKT and mammalian target of rapamycin (mTOR) in endometrial cancers where mutations in PIK3CA have been reported at high frequency in both Type I and Type II tumors." (PMID 31934607, 2020). "Several genes and pathways (including EGFR family, PI3K/Akt/mTOR, RAS/RAF/MEK/MAPK, autophagy, tumor metabolism, low PTEN, PIK3CA mutations, etc.)have been reported to be associated with lapatinib resistance and may provide inspiration for future HER2-TKI development." (PMID 33109256, 2020). "Therefore, circulating tumor DNA (ctDNA) analysis has been widely employed as a noninvasive approach to detect PIK3CA mutation status." (PMID 32461963, 2020). "Interestingly, a study showed higher expression of PIK3CA as being significantly associated with advanced NPC, thereby suggesting that increased expression of PIK3CA may contribute to tumor cell proliferation and metastasis." (PMID 32545461, 2020). "Tumor PIK3CA mutations are not clear predictors of response to mTOR inhibition." (PMID 32923864, 2019). "Two patients with MMR-D without tumor response had PS of 1 or PS of 2 as well as PIK3CA mutations." (PMID 30704511, 2019). "However, we could not completely rule out the possibility that the difference in glutamine anaplerosis between PIK3CA mutant and WT tumors is a consequence of different tumor growth rate." (PMID 31844152, 2019). "PIK3CA expression could affect multiple tumor progression as reported." (PMID 31472672, 2019). "These analyses revealed no KRAS/BRAF/GNAS/PIK3CA mutations in all tumor samples." (PMID 30116990, 2018). "In addition to the frequent PIK3CA mutations, deletions of PTEN have been observed in about 20% of ovarian clear cell carcinomas, thus supporting a role for aberrant PI3K/PTEN pathway in the development of this tumor." (PMID 29389895, 2018). "As an example, the gene PIK3CA showed a mutation in the primary tumour but not in the metastases." (PMID 30029640, 2018). "In addition, clonal selection during the metastatic process is noted, since the mutations in PIK3CA are not observed during tumor progression (only two cases had acquired PIK3CA mutations in liver metastases)." (PMID 30344942, 2018). "Pan-PI3K inhibitors may be better suited to combination therapy than inhibitors of mammalian target of rapamycin complex 1/2, and there is evidence that their activity may not be restricted to tumor types with PIK3CA mutations." (PMID 30185228, 2018).
tumor (continued). "Moreover, we investigated the KRAS/BRAF/GNAS/PIK3CA mutational status (mutational analysis for exon 2 of KRAS, exon 15 of BRAF, exons 9 and 20 of PIK3CA, and exons 8 and 9 of GNAS) of the original tumor (pancreatic head) and the recently resected tumors from the pancreatic body and tail." (PMID 30116990, 2018). "In accordance to tumor genotyping, the BRAF V600E mutation was found in the basal cfDNA of patient 9 (0.07% of plasma DNA fragments), patient 12 (10.47%), patient 17 (0.40%) and patient 18 (3.64%), and the PIK3CA H1047R mutation was found in the cfDNA of patient 18 (2.62%)." (PMID 27852040, 2017). "However, the significance of such alterations in relation to clinical outcome are not conclusive and may be related to the specific mechanism of activation (PIK3CA mutation or PTEN loss), or specific tumor subtypes." (PMID 28060766, 2017). "In our cohort, no tumor harboring PIK3CA mutation had high MEK signature." (PMID 29296181, 2017). "However, the rate of cfDNA mutations in the patients without any prior KRAS/NRAS/BRAF/PIK3CA tumor mutations was 10-fold lower than the cutoff (0.002% ± 0.00014; N = 374)." (PMID 27852040, 2017). "In the Neoadjuvant Lapatinib and/or Trastuzumab Treatment Optimization Trial (NeoALTTO), tumours with PIK3CA mutations had lower pCR rates after treatment with neoadjuvant paclitaxel plus HER2-targeted therapy, with pCR rates decreasing from 34.5% in PIK3CA WT tumours to 21.3% in mutated tumours." (PMID 28750640, 2017). "If the PIK3CA and other oncogene variants found in the ASD cohort decrease signaling activity then these oncogenes in ASD patients may be “weaker” in fueling the growth-factor independent proliferation characteristic of neoplasms." (PMID 26934580, 2016). "Genomic DNA from primary tumour tissues of 1284 consecutively-collected patients with metastatic colorectal carcinoma (mCRC), originating from different geographical areas within Sardinia island, was screened for somatic mutations in KRAS, NRAS, BRAF, and PIK3CA genes." (PMID 27737711, 2016). "Of course, since our analysis was performed on the entire tumor tissue, the possibility that AKT1 and PIK3CA mutations existed in different cells within the tumor could not be excluded." (PMID 27515171, 2016). "A different PIK3CA mutation status between primary tumors and corresponding metastatic lesions has been previously reported in FBC, indicating that PIK3CA mutations may be acquired during tumor progression." (PMID 27765917, 2016). "Our data suggests that PIK3CA mutations are not essential to tumour initiation in DIPG but may confer localized survival, growth and angiogenic advantage in the areas they are subsequently acquired." (PMID 27048880, 2016).
tumor (continued). "Functional mutations in PIK3CA (odds ratio (OR)=0.58; 95% confidence interval (CI)=0.49–0.69), GATA3 (OR=0.77, CI=0.6–0.99), MAP3K1 (OR=0.52, CI=0.4–0.68), KMT2C (OR=0.69, CI=0.52–0.94) and CBFB (OR=0.56, CI=0.38–0.83) were associated with lower grade in ER+ tumours." (PMID 27161491, 2016). "Considering these discussion points, the reason that clinically important point mutations such as EGFR (L858R, T790M) and PIK3CA (E545K) discovered in tumor samples could not be observed in matched CTCs could be explained." (PMID 27892470, 2016). "Furthermore, PIK3CA overexpression was described in other different tumor types." (PMID 26334097, 2015). "Interestingly, TLK2 overexpression can co-occur with PTEN loss or when PIK3CA, a key driver of ER-positive/luminal tumours, is not overexpressed." (PMID 26427375, 2015). "Therefore, a combination chemotherapy regimen incorporating aspirin with ABT-737 warrants clinical investigation in solid tumours, and may potentially be an efficient therapy for aspirin-resistant PIK3CA wild-type tumours." (PMID 25388762, 2015). "Additional deep sequencing confirmed that an activating PIK3CA (H1047R) mutation was present only in the primary tumor, not in the liver metastasis or cfDNA, indicating that either the mutation emerged after metastasis, or was not present in the subpopulation that seeded the metastasis." (PMID 26317216, 2015). "Consequently, their treatment regimens were changed and the EGFR T790M and PIK3CA mutations were no longer detectable in the tumor samples collected a couple of months later, and patients responded again to retreatment with an EGFR tyrosine kinase inhibitor." (PMID 25980577, 2015). "These conflicting reports were then reconciled by a large retrospective consortium analysis on 1,022 tumor samples which showed that, in the KRAS wild-type subpopulation, only PIK3CA exon 20 mutations may be predictive of lack response to cetuximab (RR of 0 % in mutant vs 36.8 % in wild-type cases)." (PMID 24811491, 2014). "Although others did not observe a significant association between PIK3CA mutations and tumor grade, this discordance could be explained by the relatively small number of patients in these studies." (PMID 24467828, 2014). "However, the same dose of P7170 was not very effective in mice bearing erlotinib-insensitive H1975 [EGFR T790M, L858R; KRAS wild type; PIK3CA wild type] xenografts, but treatment with a15 mg/kg dose resulted in a significant tumor growth inhibition (92% TGI, p < 0.001)." (PMID 25466244, 2014). "We further performed a multivariate analysis (Cox proportional hazards) with PIK3CA mutation status, histological subtype, age, gender, tumor stage, tumor grade as variable, and did not found the independently prognostic value of PIK3CA mutation in these factors." (PMID 24533074, 2014). "Additionally, when early neoplasias with a PIK3CA mutation were compared to early neoplasias without an identifiable PIK3CA mutation, no significant gene expression differences were identified between the two groups (data not shown)." (PMID 24887547, 2014). "In this hypothesis-generating analysis, the increased activity of the dual anti-HER-2 blockade with T plus L seems limited to tumours not harbouring PIK3CA mutations." (PMID 25374620, 2014). "In the cohort of patients with available tumor tissue and who provided consent, 24% (65/274) had tumors harboring PIK3CA mutations (E542K, E545K/D, and H1047R); 13% (49/390) of patients with available tumor tissue had absence of PTEN expression and 53% (205/390) had low PTEN expression." (PMID 25056500, 2014). "However, although mutations in phosphatidylinositol kinases in general have been associated with a high risk of tumour relapse, multivariate analysis did not reveal an association between mutations in PIK3CA and an increase in relapse risk." (PMID 23441137, 2013).
tumor (continued). "However, although there are limited data (n = 22), an association between BRCA1/2 loss and activation of the PIK3CA/mTOR pathway in human tumours has not been confirmed." (PMID 23971979, 2013). "In addition to the influence of tumor COX-2 expression on aspirin treatment benefit in CRC as detailed above, a recent study showed that only CRC patients bearing a mutation in PIK3CA (exon 9 or exon 20) benefitted from aspirin treatment, and not patients with wild-type PIK3CA tumors." (PMID 24759962, 2013). "To further test our hypothesis that PIK3CA mutation was responsible for the resistance to Trastuzumab therapy in a HER-2 positive esophageal PDECX model, we performed an anti-tumor efficacy combination study using Trastuzumab and the small molecule AKT inhibitor, AZD5363." (PMID 22935382, 2012). "However, a non-significant trend for PIK3CA mutations to be associated with a older age of onset and a higher tumour grade was observed." (PMID 22931052, 2012). "PTEN acts as negative modulator of PIK3CA and is mutated in many tumor types as well as in UC." (PMID 21533174, 2011). "These two AKT1 mutant tumours do not possess any mutations in PIK3CA, PTEN and K-Ras." (PMID 19491896, 2009). "Our study extends the current paradigm to imply that patients with KRAS-, BRAF- or PIK3CA-mutant tumours may all derive limited benefit from treatment with EGFR mAb, and that BRAF mutations in particular account for a measurable fraction of patients whose KRASWT tumours do not respond to cetuximab." (PMID 19603024, 2009). "However, to date it remains unknown whether PIK3CA assumes diverse roles depending on the state and/or the context in which the tumor cell is found." (PMID 18335034, 2008). "In a multivariate model that included patient ethnicity, tumor grade (1/2 versus 3), tumor size, nodal stage, ER, PR, and HER2 status, patient age as well as response to chemotherapy, nodal status remained independently associated with PIK3CA mutation (P = 0.029)." (PMID 18371219, 2008). "Treatment of an HPV16-positive, HLA-A2, PIK3CA mutant cell line (CaSki) with T cells (NexImmune), specific to HPV16 tumor antigens inhibited in a T cell: target cell ratio-dependent manner." (PMID 41646800, 2026). "In contrast, lesions in PIK3CA were observed in HR-competent tumors and were more common in luminal A subtype tumors, and we observe a similar low-HRD pattern across other tumor types." (PMID 41260881, 2026). "To our knowledge, the immunophenotype combining PIK3CA-positive and PYGO2-negative staining in HCC is rarely documented; we therefore report this case and discuss its implications for tumor biology and therapy." (PMID 41133538, 2025). "In SCCs, TERT, PIK3CA, and matrix metalloproteinases (MMPs) are common oncogenes, whereas KMT2D and CDKN2A are common tumor suppressors." (PMID 39455281, 2025). "Across tumor types, PTEN and PIK3CA showed frequent non-synonymous alterations, indicating shared drivers within the mTOR axis." (PMID 41300706, 2025). "In parallel, the PI3K/AKT pathway is a critical regulator of tumor metabolism and survival, with frequent alterations in PTEN and PIK3CA driving increased tumor invasiveness and immune evasion." (PMID 40869017, 2025). "Other tumour driver genes (NF1, ATRX, PIK3R1, SPTA, and PIK3CA) marked by IntOGen,54 were also found among the top 12 mutated genes." (PMID 41292185, 2025).